VAMP3 (vesicle associated membrane protein 3)
Diseases named in the same sentence as VAMP3 in open-access papers (continued):
Sharing a sentence is not in itself a finding about the gene and the disease.
infection (10 papers, 2016 to 2025). The state of being infected such as from the introduction of a foreign agent such as serum, vaccine, antigenic substance or organism. "As vAC generation is essential for production of infectious progeny, we used this HCMV hallmark as a molecular checkpoint to assess infection progression and function in VAMP3 KD cells." (PMID 32910773, 2020). "The results showed that VAMP3−/− mice exhibited significantly reduced bacterial titers in the cerebrospinal fluid after tail vein infection compared to wild-type mice, indicating the transcytosis of NMEC across the BBB was inhibited in VAMP3−/− mice." (PMID 40601634, 2025). "Since VAMP3 can interact with various Incs during infection with C. trachomatis serovar L2, we wondered if those Inc proteins were playing a direct role in recruiting VAMP3 to chlamydial inclusions." (PMID 33229367, 2021). "To gain a better understanding of the function that host VAMP proteins play during infection with C. trachomatis serovar L2, we wanted to characterize the effect of siRNA knockdown of VAMP3 on the development of C. trachomatis serovar L2." (PMID 33229367, 2021). "Localization of VAMP3 to the chlamydial inclusion is altered during infection with C. trachomatis serovar L2 ΔincA and C. trachomatis serovar L2 ct813::bla mutant strains." (PMID 33229367, 2021). "Infection of cells stably expressing an EGFP-tagged version of VAMP-3 revealed that VAMP-3 also localized at the site of EPEC infection (uninfected S5B Fig) in small, discrete puncta." (PMID 28636623, 2017). "We hypothesized that infection of HBMECs by NMEC can induce the expression of VAMP3 and syntaxin 4 via LPS." (PMID 40601634, 2025). "Furthermore, quantification of morulae revealed a statistically significant (P < 0.05) increase in VAMP3- or VAMP4-positive A. phagocytophilum-containing morulae over the time of post-infection from 4 hours to 48 hours." (PMID 39950824, 2025). "For example, during infection with Yersinia pseudotuberculosis, VAMP3 is recruited early to the Yersinia-containing vacuole (YCV), where it then acts as a checkpoint for the YCVs to preferentially become single-membrane, as opposed to LC3-positive double-membrane, to prevent autophagy." (PMID 33229367, 2021). "Interestingly, SNAP-23 is a t-SNARE for VAMP3, and has also been shown to localize within the vAC during infection." (PMID 32910773, 2020). "When we observed VAMP3 localization to C. trachomatis serovar L2 ct005::bla inclusions, VAMP3 localization appeared unchanged compared to that of a WT C. trachomatis serovar L2 infection, which is consistent with our data demonstrating a lack of interaction between these proteins." (PMID 33229367, 2021). "We first performed an immunofluorescence assay to examine the localization of VAMP3 and VAMP4 to the A. phagocytophilum-containing vacuoles in tick cells at different post-infection time points (4 hours, 24 hours, and 48 hours)." (PMID 39950824, 2025). "Taken together, these results indicate that expressions of VAMP3 and VAMP4 are also important for A. phagocytophilum survival at later stages of infection in tick cells." (PMID 39950824, 2025). "induces phagocytotic entry into the host cells by using VAMP8 at the entry site; recruits VAMP2, VAMP3, and VAMP4 on to the Salmonella-containing vacuoles during infection; and uses VAMP7 for secretion of typhoid toxins outside the host cell." (PMID 39950824, 2025). "Collectively, our study findings support previous observations and indicate that A. phagocytophilum enters tick cells within 4 hours and VAMP3 and VAMP4 are important for this early phase of infection." (PMID 39950824, 2025). "In this study, we provide evidence that arthropod SNARE proteins such as VAMP3 and VAMP4 are important for A. phagocytophilum entry, formation of morulae, and establishment of infection in tick cells." (PMID 39950824, 2025).
infection (continued). "We were unable to validate any VAMP4-Inc interactions during infection with C. trachomatis serovar L2, suggesting that VAMP4’s interactions at the IM are unique compared to VAMP3’s interactions." (PMID 33229367, 2021). "For these studies, we used siRNA to knock down VAMP3 or VAMP4, individually or in combination, followed by infection with C. trachomatis serovar L2 for 28 h." (PMID 33229367, 2021). "In this study, we examined the localization of endogenous eukaryotic SNARE proteins, VAMP3 and VAMP4, during infection with C. trachomatis serovar L2." (PMID 33229367, 2021). "After infection, the mRNA levels of CR3, αMβ2, αVβ3, MR, F-actin, Rab7, TUBA, DVnein, VAMP-3, VATPase, MHCI, and MHCII were up-regulated and the mRNA level of SRB1 was down-regulated." (PMID 32117165, 2020). "In a previous work we studied the recruitment of the SNARE proteins VAMP3 and VAMP7 to the parasitophorous vacuole of T. cruzi CL Brener strain at different times after infection." (PMID 33194787, 2020). "Following a 24-h infection period, analysis of acceptor cells indicated that a majority of fibrils co-localized with LAMP1 (< 30%), while smaller amounts of fibrils co-localized with EEA1 (3%) and Vamp3 (< 30%)." (PMID 35909452, 2022). "At later time points of infection, when VAMP3 localization is not as prominent, we found fewer Inc binding partners for VAMP3." (PMID 33229367, 2021). "Previously, endogenous VAMP3 was localized to C. trachomatis serovar D inclusions, but its localization has not been demonstrated during infection with C. trachomatis serovar L2." (PMID 33229367, 2021). "In this study, we provided evidence that arthropod VAMP3 and VAMP4 proteins play an important role not only in the early phase of A. phagocytophilum infection in tick cells but also in the persistent survival of this bacterium at the later stages of infection in tick cells and ticks." (PMID 39950824, 2025).
cancer (9 papers, 2018 to 2024). A tumor composed of atypical neoplastic, often pleomorphic cells that invade other tissues. "The CEBPD transcription factor enhances cancer resistance through VAMP3-mediated autophagy activation, increasing PD-L1 levels and suppressing CD8+ T-cell-mediated immune response." (PMID 39409003, 2024). "Furthermore, impeding VAMP3 recycling with WDFY2 diminishes the secretion of matrix metalloproteinases by cancer cells, necessary for remodeling the extracellular matrix." (PMID 38802855, 2024).
bacterial infection (2 papers, 2025). "The localization of VAMP3 and VAMP4 on the A. phagocytophilum-containing vacuole in cells with persistent bacterial infection prompted us to further investigate whether these proteins are important for the early phase of bacterial infection." (PMID 39950824, 2025).
nervous system disease (1 paper, 2020). "For instance, in OPC protein–protein interaction (PPI) network, proteins involved in Golgi vesicle transport (such as Vamp3, Golga7, Vti1b and Snx1), Cell redox homeostasis (such as Tnx2 and Gsr), nervous system disease (such as Got1, Gm2a, Apoe and Cst3) and other functions were identified." (PMID 32974003, 2020).
neurodegenerative disease (1 paper, 2025). A disorder of the central nervous system characterized by gradual and progressive loss of neural tissue and neurologic function. "VAMP3 has been implicated in several cellular processes including autophagy, through its role in autophagosome biogenesis and indirectly in neurodegenerative diseases such as AD, due to being regulated by the AD risk factor PICALM (Phosphatidylinositol binding clathrin-assembly protein)." (PMID 40619440, 2025).
VAMP3 also shares sentences with these, for which no sentence is quoted: Insulin resistance (3 papers); cardiovascular disease (2); coronary artery disease (2); Obesity (2); periodontal disease (2); aggressive periodontitis (1); breast tumors (1); embryonal rhabdomyosarcoma (1); inflammatory bowel disease (1); Thrombus (1); type 2 diabetes (1).